APOE (apolipoprotein E)
Diseases named in the same sentence as APOE in open-access papers (continued):
Sharing a sentence is not in itself a finding about the gene and the disease.
Cognitive impairment (continued). "The apolipoprotein E (APOE) e4 allele is strongly associated with increased risk of cognitive impairments in older adulthood." (PMID 24582638, 2014). "The association, in different ethnic groups, of apolipoprotein E (apoE) gene polymorphism with mild cognitive impairment (MCI) has been unclear." (PMID 25161798, 2014). "We also recognize that the APOE ε4 allele has been consistently linked with impaired cognition in older populations." (PMID 25085564, 2014). "A primary genetic risk factor for AD is the presence of the ε4 allele in the apolipoprotein E (ApoE) gene, and its presence is directly associated with the incidence of cognitive impairment seen in elderly individuals with mild cognitive impairment (MCI)." (PMID 24839550, 2014). "The objective of this study was to examine the associations between β-amyloid, apolipoprotein ε4 (APOE ε4) genotype, and metabolic correlations patterns in subjects diagnosed with mild cognitive impairment (MCI)." (PMID 24736891, 2014). "The apoE ε4 allele has been widely studied as a risk factor for mild cognitive impairment (MCI) and Alzheimer's disease (AD), but its impact has been found to differ across ethnic groups." (PMID 25161798, 2014). "We also attempted to minimize the influence of unadjusted confounding by including in the Models all the variables that we found to be associated with cognitive impairment or those reported in the scientific literature including APOE gene." (PMID 24736378, 2014). "A meta-analysis found that the APOE ε4 allele was associated with a moderately increased risk for progression from mild cognitive impairment to Alzheimer's disease-type dementia." (PMID 24621278, 2014). "APOE*4, however, is associated with increased risk of cardiovascular disease, stroke and Alzheimer’s disease and is a risk factor for cognitive impairment in old age and after stroke." (PMID 23957944, 2013). "Two studies have concluded that the protective effects of PA on cognitive function and the incidence of cognitive impairment are larger in those who possess a genetic risk as a carrier of the APOE-ε4 allele." (PMID 24961307, 2013). "Parasuraman and collaborators have taken a cognitive neuroscience approach to study effects of genes involved in risk of AD (APOE) or mechanisms involved in cognitive deficit in AD (cholinergic genes—CHRNA4)." (PMID 22693679, 2012). "And transgenic animal models have repeatedly shown the influence of loss of ABCA1 on apoE lipidation, Aβ production or deposition and cognitive impairment." (PMID 23181436, 2012). "Although there is also evidence of milder cognitive impairment in later life in carriers of the APOE ε4 allele, there have been few studies investigating the impact of APOE genotype on cognitive function in children." (PMID 21215387, 2011). "APOE ε4 allele results in early cognitive deficits in EAE mice, including deficits in spatial learning and recalling." (PMID 20613949, 2010). "The association between APOE ε4 allele and cognitive deficits in MS has been verified by dozens of studies." (PMID 20613949, 2010). "Our recent studies have revealed alterations in the pattern of deactivation also in elderly individuals at risk for AD by virtue of their APOE e4 genotype, or evidence of mild cognitive impairment (MCI)." (PMID 19847047, 2009). "Next, we determined whether retinal Chlamydia pneumoniae burden associates with AD-related brain pathology, apolipoprotein E (APOE) ɛ4 allele, disease staging, or the extent of cognitive deficit." (PMID 41571675, 2026). "Conversely, APOE e4-negative cases may require additional risk factors, e.g. comorbidities, to develop cognitive deficits, increasing the costs in the higher disease stages." (PMID 40571933, 2025). "Interestingly, higher plasma MMP-9 concentration has been shown to be associated with a greater risk of AD development in APOE ε4 carriers with mild cognitive impairment." (PMID 41009358, 2025).
Cognitive impairment (continued). "Notably, an individual carrying the APOE-ε4 allele exhibited the poorest mitochondrial function, highest Aβ burden, and most severe cognitive impairment, suggesting a potential interaction between genetic risk and mitochondrial health." (PMID 40002463, 2025). "This would be consistent with associations between APOE ε4 carriers and cognitive deficits in AD and may relate to some neurodegenerative processes." (PMID 40149482, 2025). "As expected, advanced age was associated with a higher risk of cognitive impairment post-stroke, consistent with the general age-related decline in cognitive function observed in other stroke populations, particularly among those carrying ApoE ε4." (PMID 40349252, 2025). "A study suggests that biophilic environments may reduce the occurrence of neuroinflammation by alleviating stress, thereby improving cognition, which is crucial in mitigating cognitive impairment associated with the E4 variant of apolipoprotein E (APOE4)." (PMID 40045967, 2025). "Within this cluster, M4, the Ubiquitination module, showed strong correlations with CSF Aβ, t‐tau, and p‐tau181, as well as APOE genetic risk (quantified by the number of APOE ε2, APOE ε3, and APOE ε4 alleles, scaled by risk) and cognitive impairment (assessed via MoCA score)." (PMID 41178698, 2025). "People with one or more APOE-ε4 allele were younger (66.56 years compared to 69.02 years), had higher proportion of very mild cognitive impairment (23 % compared to 16 %), lower MMSE (28.67 compared to 28.99), and higher Aβ burden (29.57CL compared to 11.33CL)." (PMID 41270680, 2025). "Within this cluster, M4, the Ubiquitination module, showed strong correlations with CSF Aβ, total tau, and pTau181, as well as APOE genetic risk (quantified by number of the APOE2, APOE3 and APOE4 alleles, scaled by risk) and cognitive impairment (assessed via MoCA score)." (PMID 40161719, 2025). "The goals of this exploratory, cross-sectional study were to determine the contribution of apolipoprotein E4 (APOE4) gene presence, identify plasma proteins associated with cognitive impairment, and validate our findings with another platform that has clinical utility." (PMID 41369364, 2025). "The distinct NEEV-miRNA profiles and their associations with metabolic burden and APOE genotype suggest that population-specific genetic and health risk factors may shape molecular signatures of cognitive impairment." (PMID 41294837, 2025). "APOE ε4 carriers are more susceptible to Aβ deposition and synaptic damage, which accelerates the transition from subjective memory complaints to clinical cognitive impairment." (PMID 40766179, 2025). "However, the only study specifically conducted on cognitive impairment/decline showed a decreased risk for higher fish consumers among APOE ε4 allele carriers (RR = 0.18, 95% CI: 0.05–0.63)." (PMID 39162889, 2024). "Similarly, the AD and objective cognitive impairment groups carried more APOE ε4 alleles compared with the corresponding groups." (PMID 39050136, 2024). "Our previous research has demonstrated that aging, ApoE ε4 allele and decline in olfactory function may serve as indicators of cognitive impairment in T2DM patients." (PMID 38660514, 2024). "The apolipoprotein E (APOE) ε4 allele carries risk for cognitive impairment, but whether the level of circulating apoE4 protein in carriers affects cognition is unclear, as is how health and lifestyle impact circulating apoE4 levels." (PMID 39234633, 2024). "Importantly, ApoE-deficient mice show decreased locomotor activity in novel environments and learning and memory deficits, consistent with cognitive impairment and memory loss." (PMID 38891031, 2024). "However, the authors reviewed the literature using PubMed, and their review revealed that the relationship between APOE‐associated synaptic loss and cognitive impairment remains incompletely understood." (PMID 38477490, 2024).
Cognitive impairment (continued). "Furthermore, after adjustment for age, BMI, sex, study site, years of education, CESD depressive symptoms score, and presence of the APOE e4 allele, longer sleep latency was associated with increased likelihood of cognitive impairment later in life." (PMID 38903901, 2024). "The APOE e4 allele and Lewy body pathology are more common in AD patients with hallucinations, suggesting that the APOE e4 allele might mediate cognitive impairment in the AD endophenotype with hallucinations, possibly via Lewy body neuropathology." (PMID 38473892, 2024). "APOE ε4 allele that encodes APOE increases the cognitive defect." (PMID 39355336, 2024). "However, those with both the APOE e4 allele and loneliness were five times more likely to experience cognitive impairment." (PMID 38962235, 2024). "While they indicate that SCD status and APOE ɛ4 positivity increase risk of developing objective cognitive impairment, they note that a limited understanding of the relationship between SCD and APOE status remains, especially given the paucity of studies that have employed longitudinal cohorts." (PMID 38253819, 2024). "The association of ApoE glycosylation and Aβ was further demonstrated in plasma samples collected from a cohort of older individuals with a mean age of 75.6 years and 49% with cognitive impairment." (PMID 39169951, 2024). "We studied whether African and Amerindian ancestry-enriched genetic variants in the APOE region modify the effect of the APOE-ɛ4 alleles on Mild Cognitive Impairment (MCI) in Hispanics/Latinos." (PMID 36991100, 2023). "Interaction of ApoE polymorphism with VEGF genes has been shown to affect cognitive impairment in AD patients as increased levels of Neuropilin 1 (NRP1), a member of VEGF family in AD patients has been shown to be associated with improved cognition in ApoE4 non-carriers." (PMID 37199411, 2023). "We next performed logistic analyses to evaluate whether the ApoE polymorphism is independently associated with cognitive impairment in T2DM patients." (PMID 37700547, 2023). "As hypertensive arteriopathy and CAA are the most common sporadic types of microangiopathy in ICH, several factors associated with CAA have been identified as predictors of post‐ICH cognitive impairment, including age, the ApoE ε4 allele, lobar hematoma, and cSS." (PMID 37533346, 2023). "The reduced BBB clearance function of amyloid β (Aβ) associated with APOE ε4 burden may also apply to cognitive impairment in MS as in early AD." (PMID 37397465, 2023). "However, similar findings among APOE ε4 carriers with subjective cognitive impairment and higher CSF ApoA1 have been associated with an increased risk of clinical progression toward AD." (PMID 36927447, 2023). "However, other risk variables include male sex, the presence of the apolipoprotein E allele, a family history of cognitive impairment, and several vascular risk factors, including hypertension, hyperlipidemia, coronary artery disease, and stroke." (PMID 37569657, 2023). "Several single‐nucleotide polymorphisms (SNPs) present in apolipoprotein E (APOE) gene have previously been associated with neuroimaging measures in both cognitively healthy control (HC) or impaired (such as mild cognitive impairment [MCI] and AD dementia) patients." (PMID 36575854, 2023). "It has been suggested that rs7259620 is associated with neuropathic features and that the AA genotype in the ApoE gene may be an independent risk factor for cognitive impairment compared with other genotypes." (PMID 37644506, 2023). "We entered multiplicative interaction terms for Lifetime incarceration and APOE-ε4 genotype into our analysis (Model 2.5) and found that neither term (i.e., for one copy or two copies) predicted excess risk of cognitive impairment that was distinguishable from the additive effects." (PMID 38048316, 2023).
Cognitive impairment (continued). "In this study, as a first contribution, we have presented a causal data generation approach for assessing the transportability of prediction models for cognitive impairment in synthetic external settings with different distributions of age, APOE ε4 allele frequency, and tau." (PMID 37598141, 2023). "The current study highlights that APOE ε4 allele may accelerate the senescence of hippocampal neurons by decreasing Ac‐CoA level and in turn lead to the cognitive impairment, which pinpoints an under‐recognized role of the APOE ε4 allele." (PMID 37594184, 2023). "In fact, the lack of apoE has been previously associated with BBB breakdown, increased BBB susceptibility to injury, and exacerbation of brain edema after brain trauma, explaining the cognitive impairment presented by apoE-deficient mice after closed head injury." (PMID 37111572, 2023). "In addition, CU individuals with the apolipoprotein E ε4 allele (APOE ε4), cerebral amyloid burdens, and cortical atrophy were more likely to progress to cognitive impairment." (PMID 36993907, 2023). "Moreover, a study conducted by Oliveri and co-authors found that the APOE gene−491A/T polymorphism is associated with severe cognitive impairment in patients with MS with a homozygous AA genotype." (PMID 35885971, 2022). "However, future research is needed to further clarify the influence of ApoE polymorphism and serum tHcy level on cognitive impairment with the larger and longitudinal study." (PMID 35351068, 2022). "Furthermore, loss of ApoE disrupts the blood–brain barrier in aging mice and leads to cognitive impairment and cerebrovascular dysfunction." (PMID 36188475, 2022). "Cognitive impairment in the elderly may be associated with genetic factors such as polymorphisms in apolipoprotein E allele (ApoE4 variants) and hemochromatosis gene (HFE C282Y variant)." (PMID 35162428, 2022). "Another explanation is that tHcy affects the development of cognitive impairment in various pathways, which all may be modulated by the ApoE polymorphism." (PMID 35351068, 2022). "In addition, Apolipoprotein E (ApoE) genotype is an important genetic risk factor for cognitive impairment, and is correlated with diminished physiological complexity as measured by HRV." (PMID 36420310, 2022). "In addition, female APOE-e4 carriers are more likely to progress from mild cognitive impairment (MCI) to AD, have more brain atrophy and memory loss, and develop AD more frequently than age-matched males." (PMID 35573689, 2022). "For subjects with mild cognitive impairment, beyond APOE, a more inclusive polygenic risk score including more variants, shows coronary artery disease-polygenic risk score to be more predictive of whole-brain volume atrophy, than an oligogenic approach including fewer larger effect size variants." (PMID 36523268, 2022). "Our findings suggest that a higher genetic risk of AD beyond ApoE status may drive similar mechanisms that lead to cognitive impairment and deficits in working memory." (PMID 35645768, 2022). "As expected, APOE ε4 was a significant risk factor for cognitive deficits in the pcb-Cohort." (PMID 39081475, 2022). "LOAD-PGR was associated with smaller hippocampal volumes and aspects of cognitive ability in healthy adults and could supplement APOE status in risk stratification of cognitive impairment/LOAD." (PMID 34621014, 2022). "In addition, our observations are likely credible because the trend of association between APOE ε4 and cognitive impairment occurred despite the similarity in potential clinical confounders such as age at onset, duration of PD and age at study." (PMID 36371506, 2022). "In fact, WD-fed ApoE−/− mice have previously been demonstrated to successfully reproduce spatial cognitive deficits (memory loss) and anxiety status through a dysregulation of the HPA axis that regulates GCs synthesis, which plays an important role in several brain functions." (PMID 36077225, 2022).
Cognitive impairment (continued). "However, this study provided no longitudinal data or evidence of the mechanisms underlying the association between APOE-ε4 and lower FM in older women with cognitive impairment." (PMID 35276898, 2022). "Overall, the APOE ε4 allele may lead to a dysregulation of the vascular structure and function with reduced cerebral perfusion, which in turn leads to cognitive impairment." (PMID 35847686, 2022). "As MDD and APOE ε4 status are both associated with cognitive impairment, Piers and colleagues also assumed that the APOE ε4 allele might influence the association between depressive symptoms and cognitive impairment." (PMID 35884866, 2022). "A recent Chinese study revealed that exosomal SNAP25, GAP43, neurogranin, and synaptotagmin-1, combined with APOE ε4 status, improved diagnostic accuracy (AUC = 0.88), acting as a useful biomarkers panel for the prediction of AD five to seven years before cognitive impairment." (PMID 35360215, 2022). "As expected, APOE-ε4 is associated with an increased risk of cognitive impairments." (PMID 34301914, 2021). "We hypothesized that the ApoE polymorphism rs429358 would lead to the changes in ApoA1 and ApoB levels, thereby playing a role in cognitive impairment in schizophrenia." (PMID 34135129, 2021). "We show that the APOE ɛ4 allele drives progressive cognitive impairment in PD." (PMID 33111402, 2021). "The large cognitive deficits on the delayed word list recall in AD may therefore be attributed to factors other than the APOE e4 allele." (PMID 34194377, 2021). "Therefore, we evaluated the effects of the APOE-ε4 allele on the cholinergic structural association and neurocognitive performance in groups with different levels of cognitive impairment." (PMID 34721251, 2021). "Notably, the more pathogenic clusters also show higher PPR, cognitive impairments and frequency of putative APOE alleles." (PMID 34704025, 2021). "ApoE gene polymorphism may be involved in the change in blood lipid profile and cognitive impairment of the general population." (PMID 34135129, 2021). "Therefore, it was difficult to obtain multiple screening tools for cognitive impairment measurements and identification of individual participant’s ApoE genotype, which is known to be a genetic risk factor for cognitive and cardiovascular diseases." (PMID 34830687, 2021). "APOE ε4 allele has also shown association with cognitive impairment in PD8." (PMID 34376695, 2021). "In addition, the risk of cognitive impairment of APOE ε4 carriers vs. non-ε4 carriers was equivalent to 2.5 additional years of aging, and also equivalent to decreasing greenness by 0.38 units." (PMID 31919381, 2020). "In addition, the risks of APOE ε4 allele carriage on cognitive impairment were only significant among the adults aged 65 to 79 years but not for the adults aged 80 years and older, although the association was weak." (PMID 31919381, 2020). "APOE ε4 carriers showed altered protein levels of complement related proteins in the normal cognition stage, while lower levels of proteins associated with cell adhesion and synaptic signaling were found in cognitive impairment stages." (PMID 32460813, 2020). "APOE gene is considered an important risk factor for AD and cognitive impairments." (PMID 32694990, 2020). "Further studies with larger sample size may have the condition to explore if the APOE‐ε4 allele is independent or has synergistic effects with other risk factors for cognitive impairment." (PMID 32864870, 2020). "A large cross-sectional study consisting of 10,039 Chinese community-dwelling participants aged ≥55 years indicated that high serum UA was associated with a decreased risk of cognitive impairment after adjusting for age, sex, lifestyle, relevant diseases and the apolipoprotein E (APOE) ε4 allele." (PMID 32819289, 2020).